ALK (ALK receptor tyrosine kinase)
Diseases named in the same sentence as ALK in open-access papers (continued):
Sharing a sentence is not in itself a finding about the gene and the disease.
tumor (continued). "Recent studies have shown that sensitivity of EGFR ctDNA is lower for tumor tissues, while the data for ALK rearrangement assessment using ctDNA is relatively limited compared with EGFR mutations." (PMID 32974126, 2020). "Particularly, the ALK status was accurately distinguished from conventional 4 μm thickness of 2–3 surgical or 6–8 biopsy tissue sections with as low as 5% tumor cells/slide dependent on high sensitivity and specificity of the assay." (PMID 32543087, 2020). "The same study showed that inhibition of YAP re-enhanced the anti-tumor effect of ALK inhibitors in vitro and in vivo." (PMID 32466572, 2020). "The effectiveness of ALK inhibitors on the CNS depends on several factors and it seems to be related to both the tumor molecular characteristics and the drug pharmacokinetic features." (PMID 33352844, 2020). "The patient exhibited concomitant regression of both primary tumor and multiple metastatic lesions after treatment with ALK-inhibitor despite the heterogeneous TIME." (PMID 33352665, 2020). "The metabolic shift was mediated through ALK phosphorylation of the tumour-specific isoform of pyruvate kinase (PKM2), resulting in decreased enzymatic activity." (PMID 31924270, 2020). "The incidence of tumor associated EGFR mutation and anaplastic lymphoma kinase (ALK) rearrangement varies from 10% (in the USA) to 35% (in East Asia) and 5–7%, respectively, in patients with NSCLC." (PMID 32770960, 2020). "The patient with the most robust recorded response (44.8% tumor regression) was a 21-year-old woman with metastatic inflammatory myofibroblastic sarcoma (with ALK fusion) who received three cycles of nivolumab plus crizotinib before progression." (PMID 32503455, 2020). "With regard to the use of ceritinib in children, an acceptable tolerability of the drug at a dose of 510 mg/m2 was observed in a study with 22 patients with an ALK-positive tumour." (PMID 32224911, 2020). "Most of the MPLA patients in our study had high TNM stages (III-IV, 86.6%), indicating that ALK-positive status was related to advanced tumour stage." (PMID 32690092, 2020). "Molecular analyses revealed that the tumor was negative for epidermal growth factor receptor (EGFR) mutations and anaplastic lymphoma kinase (ALK) gene rearrangements and that >90% of the tumor cells expressed programmed death ligand 1 (PD‐L1)." (PMID 32181993, 2020). "Tumor tissue uses a threshold of 15% of ALK-translocated cells to diagnose a patient as ALK-positive." (PMID 32549278, 2020). "These fusions were both confirmed with testing of a post‐ALK inhibitor pericardial tumor biopsy with the Illumina TST170 NGS platform." (PMID 31747139, 2020). "In conclusion, our data indicate ceritinib/dasatinib as a new TKI combination to be tested in a clinical study not only for OS patients but also for other IGF and ALK driven tumor entities." (PMID 32224911, 2020). "Potential examples of such tumor-agnostic targets other than NTRK include (but not limited to) ALK, BRAF, BRCAness, FGFR, HER2, HER3, homologous recombination deficiency (HRD), KRAS, RET, ROS1, tumor mutation burden (TMB) high." (PMID 31974683, 2020). "The eradication of tumors in the initial phase of treatment, before the tumor develops complex heterogeneous acquired resistance, is a hypothetical strategy to cure ALK-rearranged cancer." (PMID 31900393, 2020). "Most patients with ALK-targeted therapy will inevitably develop drug resistance, leading to tumor progression." (PMID 33203201, 2020). "In this prospective study, we demonstrated the value of ctDNA analyses in NSCLC patients harboring ALK rearrangements in their tumor." (PMID 32290439, 2020).
tumor (continued). "The CCR4 is expressed in approximately 30–65% of PTCL tumor cells, including high expression (~ 65%) in ALK− ALCL, variable expression (30–40%) in PTCL-NOS, AITL, and transformed mycosis fungoides (MF), while rarely expressed in ENKTL or ALK+ ALCL." (PMID 33292562, 2020). "This ALK DNA vaccine also resulted in a 60% reduction in tumor number with survival doubling in ALK-positive NSCLC mouse models." (PMID 32059449, 2020). "In the study by Pailler and colleagues, they demonstrated that four or more ALK-rearranged CTCs per mL of blood gave a sensitivity and specificity of 100% when compared to tumor tissue." (PMID 32549278, 2020). "The interest in this tumor has also been fortified by the availability of targeted therapies, such as ALK inhibitors alectinib and crizotinib in tumors demonstrating ALK rearrangement." (PMID 31936678, 2020). "In line with this idea, doxycycline-induced ALK silencing inhibited tumor growth and increased the survival of animals bearing GICs-derived intracranial xenografts." (PMID 32308772, 2020). "Interphase FISH performed on xenograft tumour cells demonstrated an ALK translocation consistent with the original tumour (representative image from diagnosis xenograft)." (PMID 32684628, 2020). "We have investigated the relationship between serum tumor markers (CEA, SCCAg, CYFRA21‐1, and NSE) and ALK mutations in the patients in our region." (PMID 31489711, 2020). "Functionally, gene fusion involving STRN leads to constitutive activation of ALK kinase via dimerization mediated by the 5′ coiled-coil domain in the gene, while investigation of the role of the gene itself in tumour progression was neglected in most studies." (PMID 32280692, 2020). "Gilteritinib also binds to and inhibits the wild-type and mutated forms of anaplastic lymphoma kinase (ALK), resulting in reduced tumor cell proliferation in cancer cell types that overexpress the mutation." (PMID 32477567, 2020). "This rare phenomenon suggests that the diagnosis of a GIST cannot be excluded absolutely if a tumor exhibits ALK expression." (PMID 32005261, 2020). "Patients with a higher level of PDL1 expression and high tumor mutational burden (TMB) have a higher response rate, and those with EGFR-/ALK- were better than those with EGFR+/ALK+." (PMID 32542150, 2020). "ALK plays an important role in tumorigenesis, and it is expressed at high levels in some types of tumor." (PMID 32344689, 2020). "This novel cell model was used to investigate the effect of disrupting ALK fusion protein oligomerization on tumor cell growth in vitro and in vivo using nude mice." (PMID 32300555, 2020). "The present study also showed that ALK expression actually influenced tumour 18F-FDG uptake and lesion distribution." (PMID 31924270, 2020). "We also demonstrated that exogenous administration of synthetic EML4cc peptides suppressed ALK phosphorylation and tumor cell growth in EML4-ALK positive cells." (PMID 32300555, 2020). "In tumor biopsy, ALK is determined to be positive when >50% of counted nuclei (typically out of 50) are positive." (PMID 32549278, 2020). "Complete resection of the tumor is considered the treatment of choice with the prognosis depending on the tumor size (less than or equal to 3 cm) and ALK reactivity." (PMID 30632123, 2020). "Ten cases in this study exhibited inconsistent intersample ALK FISH results in their tumor tissues collected before ALK TKI administration, but from different anatomic sites." (PMID 32674491, 2020). "On molecular study, the tumor showed ALK gene rearrangement, both by immunohistochemistry and fluorescence in-situ hybridization, which has been reported only twice previously." (PMID 32149365, 2020). "On immunohistochemical staining, the tumor was positive for vimentin and anaplastic lymphoma receptor tyrosine kinase (ALK) and showed a positive signal pattern on ALK fluorescence in situ hybridization (FISH) test." (PMID 31641928, 2020).
tumor (continued). "There are different theories about the coexistence of EGFR mutations and ALK rearrangement in NSCLC—the two gene alterations coexist in different areas (i.e., different cells) of the tumor or are present in the same tumor cells." (PMID 33363040, 2020). "An AGK‐BRAF fusion was newly identified in postmortem tumor specimens from a donor with a known EML4‐ALK fusion and resistance to ALK inhibitor therapy." (PMID 31747139, 2020). "Histologic assessment of the xenografts confirmed features comparable to the original patient tumour; epithelioid morphology, ALK and CD30 staining." (PMID 32684628, 2020). "In EML4-ALK cancer cell lines, administration of synthetic EML4cc peptide elicited a decrease of phosphorylation of ALK leading to reduction in tumor cell growth." (PMID 32300555, 2020). "In our DmrB-ALK_wt model, which allows dimerization to be disrupted, phosphorylation of ALK and its downstream signals significantly decreased so that tumor growth was completely suppressed both in vitro and in vivo." (PMID 32300555, 2020). "We first evaluated the radiologic features of the primary tumor in RET+ NSCLC compared to ALK+ or ROS1+ NSCLC." (PMID 32183422, 2020). "In the population with tumor ALK fusion, two patients received combination therapy, and both had progressive disease after two cycles." (PMID 33102221, 2020). "Here, the authors show that YAP1 activation upon alectinib treatment leads to therapy resistance and that inhibiting both YAP1 and ALK leads to longer tumor remission in mice." (PMID 31900393, 2020). "The most important indication for ALK TKI administration, as well as the definitive predictive marker for a potential good response, is the ALK rearrangement in the tumor tissues." (PMID 32674491, 2020). "During the previous decades, numerous genetic variations have been described in NSCLC, including epidermal growth factor receptor (EGFR), KRAS and anaplastic lymphoma kinase (ALK), as the most commonly altered oncogenes acting as tumor driver genes." (PMID 33022831, 2020). "ALK tyrosine kinase inhibitors (ALK-TKI) have anti-tumor activities in NSCLC with ALK rearrangements, but complete cancer control has not been achieved due to acquired resistance." (PMID 32300555, 2020). "In summary, EGFR/ALK co-alterations can define a specific subgroup with tumor heterogeneity and diverse responses." (PMID 33363040, 2020). "Our work also demonstrates that the pharmacological targeting of the MDK/ALK axis efficiently acts on the population of GICs in vitro and in tumor xenografts." (PMID 32308772, 2020). "Tumor volumes in patients with ALK-rearranged NSCLC significantly decreased during the ALC treatment and all patients achieved disease control." (PMID 31900393, 2020). "Prior to testing BV and ALK inhibitor combinations against the eIMS xenografts, combination studies were performed in non-tumour-bearing mice to confirm tolerability of each combination." (PMID 32684628, 2020). "In view of these findings, a more in-depth understanding of ALK signalling and how downstream target genes impact tumour biology and therapy resistance is of great importance and remained unresolved thus far." (PMID 31937834, 2020). "For both patient A6580 and patient A6912, xenografted tumours at each site were highly correlated with the patient sample, including conservation of MYCN and ALK amplification, chromosome 1p loss and chromosome 17q gain in each." (PMID 31919402, 2020). "Because only two cases with ALK-positive tumours were identified in the EGFR/KRAS wild-type group, these data were not statistically analysed." (PMID 30953094, 2019).
tumor (continued). "The median time from tumor diagnosis to ALK status confirmation was five days (range: 0–81 days), with median times of seven days (range: 0–81 days) for NGS, seven days (range: 0–55 days) for FISH, and four days (range: 0–42 days) for IHC." (PMID 31144459, 2019). "In this study, ALK-rearrangement can be detected in CTCs captured by Nano Velcro system, presenting high concordance with matched primary tumor tissues." (PMID 30658713, 2019). "About 4% of patients with NSCLC have a specific chromosomal rearrangement that generates a tumor-specific fusion gene between the EML4 gene (echinoderm microtubule-associated protein-like 4′) and the ALK gene (anaplastic lymphoma kinase)." (PMID 31911803, 2019). "One of the mechanisms allowing tumor cells to overcome ALK oncogene addiction involves the activation of bypass signaling pathways." (PMID 30813562, 2019). "Kwang-Huei Lin’s group studied lncRNAs in ALK-positive ALCL by comparing the expression of matched tumor samples with normal tissue samples through a lncRNA-microarray." (PMID 31052302, 2019). "Monoclonal antibodies (McAbs) which target tumors mainly include drugs that target tumor-driving genes, inhibit protein kinase complexes by targeting the fusion mutation of EGFR, ALK, etc., or drugs which target angiogenesis (e.g., axitinib or sorafenib)." (PMID 31014381, 2019). "CXCR3 was expressed in the tumor cells in 8/13 ALK− ALCL cases (61%), 6/11 ALK+ ALCL cases (55%) and 5/11 cHL cases (45%)." (PMID 31581676, 2019). "Our findings demonstrated that NPM-ALK/STAT3-driven miR-135b potentiates tumor progression via multiple targets—including FOXO1, STAT6, GATA3, and PPP2R5C—in ALK-positive ALCL." (PMID 31878193, 2019). "In our study, tumor specimens were previously analyzed for the determination of EGFR and ALK mutational status, by Sanger sequencing and FISH, respectively, according to recommendations at that time." (PMID 31443496, 2019). "Tumours driven by either ALK or ROS1 involving fusion genes exhibit similar mechanisms of resistance to targeted agents." (PMID 31795465, 2019). "While the ALK associated lincRNA was also expressed in NB cell lines, expression of up to 11% of MYCN associated lincRNAs was restricted to NB tumor samples." (PMID 30952905, 2019). "We further verified the clinical relevance of active YAP in tumor biopsies of patients with resistance to ALK inhibitors." (PMID 31633304, 2019). "The median time from tumor diagnosis to EGFR or ALK status confirmation was 7 and 5 days, respectively." (PMID 31144459, 2019). "For MYCN and ALK, this was evaluated by grouping tumor samples based on driver gene status (i.e. amplified and mutated respectively) followed by differential lincRNA expression analysis." (PMID 30952905, 2019). "These authors also emphasized that analysis of ≥60 cells from ≥4 selected tumor areas is considered as a minimum requirement for accurately testing the status of ALK in NSCLC specimens." (PMID 31412611, 2019). "Additional tumor material is required for interrogating predictive biomarkers, using IHC (e.g., ALK, ROS1, PD-L1), in situ hybridization (ISH; e.g., ALK, ROS1) or sequencing techniques (e.g., EGFR, BRAF V600E, etc.)." (PMID 30818873, 2019). "As ALK mutations status opens up an excellent opportunity for application of small molecule inhibitors targeting ALK, early and sensitive detection of ALK alterations is clinically important considering its potential role in tumour progression." (PMID 30778092, 2019). "We have described a promising strategy taking advantage of the proapoptotic properties of ALK-derived peptides for ALK-dependent tumor cells which enhances the cytotoxic effect of an ALK TKI." (PMID 30813562, 2019). "Fluorescence in situ hybridization (FISH) using tumor tissue is the gold standard for detection of anaplastic lymphoma kinase (ALK) rearrangement in non-small cell lung cancer (NSCLC)." (PMID 31154543, 2019).
tumor (continued). "Immunostaining of the tumor material showed a significant increase in CD31 for both ALK inhibitors compared to the control group, indicating increased density of blood vessels." (PMID 31852910, 2019). "In 21 ALK-positive patients, the ratio of ALK-rearrangement CTC positively correlated to the ratio of ALK positive cells in tumor tissue." (PMID 30658713, 2019). "The patients with ALK-positive NSCLC have a high risk of developing CNS metastasis, as observed in ~30% of cases at the time of tumor diagnosis and in 50–60% of patients during crizotinib treatment." (PMID 31696059, 2019). "The strong inhibition of c-Met-dependent and ALK-dependent proliferation, migration, and invasion of tumor cells can directly suppress the metabolic activities of tumor cells." (PMID 31208363, 2019). "Both cases were also positive for TFAP2B and ALK, what suggests that these tumours expressed fusion positive signature." (PMID 31493794, 2019). "Critically, despite wild-type ALK expression being typically restricted to neural tissues, expression of the NPM1-ALK fusion protein ectopically occurs in NPM1-ALK+ tumour cells via the NPM1 promoter as a result of the t2;5(p23;q25) translocation." (PMID 31366041, 2019). "On the other hand, anaplastic lymphoma kinase (ALK) expression was positive in the tumor, suggesting the tumor has malignant potential." (PMID 31342196, 2019). "Among the EGFR wild-type group, 12 patients had KRAS mutations, 2 had ALK-rearrangements and 21 patients had EGFR/KRAS/ALK wild-type tumours." (PMID 30953094, 2019). "Several groups have shown Hsp90 inhibitors are active in vitro and in vivo to kill ALK-positive tumor cells." (PMID 30813562, 2019). "To explore the clinical relevance of our findings, we assessed the expression pattern of YAP in tumor biopsies acquired before and/or after ALK inhibitor therapy from 17 ALK‐positive patients." (PMID 31633304, 2019). "While tumour response data were collected from 66 patients, here, we present response data only for patients with ALK-positive tumour samples (n = 22) receiving the RP2D (40 mg Q8h)." (PMID 31217479, 2019). "Most importantly, as indicated by experimental studies, future clinical improvement for patients bearing ALK-positive tumors will likely stem from associating an ALK TKI with one of these alternate therapies, bringing synergy to kill tumor cells." (PMID 30813562, 2019). "This is further supported by another study showing that NB patients with tumours that harbor ALK alterations have a decreased 5-year overall survival as compared to those with wildtype ALK39." (PMID 30778092, 2019). "Instead, the increased desmin suggests that tumor stress by ALK TKI treatment leads to hypoxia and subsequent angiogenesis and the recruitment of pericytes that bring about the overall increase of CD31-positive vessels." (PMID 31852910, 2019). "Two additional OLIG2 positive cases showed inconclusive FISH results, but were positive for TFAP2B and ALK, what suggests that these tumours expressed fusion positive signature." (PMID 31493794, 2019). "Only three cases have ever been reported with concurrent ALK/ROS1 fusions in the same tumor indicating tumor heterogeneity." (PMID 31828041, 2019). "Tumor cells also showed diffuse and strong positivity for ALK(Roche, D5F3), which is found to be located in the cytoplasm and cell membrane." (PMID 31627758, 2019). "In one patient with a RANBP2-ALK eIMS, ALK-positive cells were detectable in tumor resected after crizotinib treatment." (PMID 32914017, 2019).